OR7D2 (olfactory receptor family 7 subfamily D member 2)
Description:
Odorant receptor.
Synonyms: OR19-4; HTPCRH03; FLJ38149; OR19-10
Tractability: Antibody: UniProt places it where antibodies can reach, with medium confidence; UniProt predicts a signal peptide or a membrane-spanning region; its Gene Ontology location is reachable by antibodies, with medium confidence. PROTAC: its protein half-life has been measured.
Gene: Protein-coding gene on chromosome 19 (9,178,979 to 9,188,818, forward strand). Ensembl gene ENSG00000188000.
Subcellular location: Cell membrane
Pathways (Reactome):
Sensory Perception: Expression and translocation of olfactory receptors
Gene Ontology:
Molecular function: protein binding; olfactory receptor activity; G protein-coupled receptor activity
Biological process: regulation of DNA-templated transcription; signal transduction; detection of chemical stimulus involved in sensory perception of smell; G protein-coupled receptor signaling pathway
Cellular component: plasma membrane; membrane
Genetic constraint (gnomAD): Loss-of-function variants: 1 observed, 0.17 expected, observed/expected ratio (o/e) 5.84. That is too few expected variants to judge how well the gene tolerates losing a copy. Missense variants: 370 observed, 404.28 expected, observed/expected ratio (o/e) 0.92, 90% interval 0.84 to 1. Synonymous variants: 158 observed, 167.69 expected, observed/expected ratio (o/e) 0.94, 90% interval 0.83 to 1.08.
Homologues: Orthologues: chimpanzee OR7D2 (98% identical), macaque OR7D2 (95% identical), dog OR7D2 (89% identical), pig OR7D2 (68% identical). Paralogues in human: OR7D4 (68% identical), OR7C1 (65% identical), OR7A10 (64% identical), OR7A5 (63% identical), OR7A17 (63% identical), OR7C2 (63% identical), OR7G3 (62% identical), OR7E24 (60% identical), OR7G2 (59% identical), OR1M1 (57% identical), OR1J4 (55% identical), OR1F1 (55% identical), and 116 more.
Diseases named in the same sentence as OR7D2 in open-access papers:
OR7D2 is named in the same sentence as 1 disease in open-access papers, as found by Europe PMC text mining. Sharing a sentence is not in itself a finding about the gene and the disease.
OR7D2 shares sentences with these, for which no sentence is quoted: breast carcinoma (1 paper).